FAM3C (FAM3 metabolism regulating signaling molecule C)
Description:
May be involved in retinal laminar formation. Promotes epithelial to mesenchymal transition.
Synonyms: ILEI; GS3786; GS3876
Tractability: Antibody: its Gene Ontology location is reachable by antibodies, with high confidence; UniProt places it where antibodies can reach, with medium confidence; UniProt predicts a signal peptide or a membrane-spanning region. PROTAC: ubiquitination databases record sites on it; its protein half-life has been measured.
Gene: Protein-coding gene on chromosome 7 (121,347,792 to 121,398,471, reverse strand). Ensembl gene ENSG00000196937.
Subcellular location: Secreted; Cytoplasmic vesicle
Subcellular location (Human Protein Atlas): Golgi apparatus; Predicted to be secreted
Pathways (Reactome):
Hemostasis: Platelet degranulation
Gene Ontology:
Molecular function: protein binding; cytokine activity
Biological process: signal transduction
Cellular component: extracellular exosome; Golgi apparatus; extracellular region; platelet dense granule lumen; cytoplasmic vesicle
Genetic constraint (gnomAD): Loss-of-function variants: 6 observed, 13.06 expected, observed/expected ratio (o/e) 0.46, 90% interval 0.25 to 0.91. The upper end of that interval is the gene's LOEUF score, 0.91, which puts it in group 3 of 6, group 1 being the genes least tolerant of losing a copy. Missense variants: 100 observed, 139.15 expected, observed/expected ratio (o/e) 0.72, 90% interval 0.61 to 0.85. Synonymous variants: 44 observed, 45.06 expected, observed/expected ratio (o/e) 0.98, 90% interval 0.77 to 1.25.
Homologues: Orthologues: chimpanzee FAM3C (99% identical), macaque FAM3C (99% identical), dog FAM3C (99% identical), guinea pig FAM3C (98% identical), pig FAM3C (96% identical), mouse Fam3c (94% identical), rat Fam3c (94% identical), rabbit FAM3C (79% identical), tropical clawed frog fam3c (79% identical), zebrafish fam3c (65% identical), Caenorhabditis elegans famp-1 (33% identical). Paralogues in human: FAM3D (50% identical), FAM3A (49% identical), FAM3B (34% identical).
Diseases named in the same sentence as FAM3C in open-access papers:
FAM3C is named in the same sentence as 64 diseases in open-access papers, as found by Europe PMC text mining. Sharing a sentence is not in itself a finding about the gene and the disease. The quoted sentences say what the papers report.
breast carcinoma (19 papers, 2014 to 2025). "Given the role of PCBP1 in our mouse model of mammary carcinoma and the increase in FAM3C and LIFR expression following loss of PCBP1, we sought to identify the mechanism(s) governing LIFR expression in mammary epithelium." (PMID 37927213, 2023). "Recently, the FAM3 metabolism-regulating signaling molecule C (FAM3C) produced by cancer-associated adipocytes (CAA) was shown to promote a metastatic phenotype in breast cancer cells, consistent with data showing that upregulation of FAM3 was correlated with poor prognosis in several cancers." (PMID 39624081, 2024). "The preceding analysis suggests a transcriptomic pattern downstream of FAM3C/LIFR/STAT3 modulation that is specifically implicated in mammary carcinoma pathology and that is exemplified by changes in the regulation of an established mediator of EMT and cell fate, TWIST1." (PMID 37927213, 2023). "Moreover, because breast cancer cells had been previously shown to secrete FAM3C protein, it is of great significance to determine the association between circulating FAM3C protein and breast cancer progression in future." (PMID 30887707, 2019). "Because FAM3C overexpression or silencing is associated with HSF1 mRNA level change in breast cancer cells, it is reasonable to speculate that FAM3C enhanced HSF1 gene transcription." (PMID 30887707, 2019). "Following shRNA knockdown of FAM3C in human cell lines, qPCR analysis revealed a measurable loss of LIFR mRNA levels relative to control cells, demonstrating a correlation between LIFR and FAM3C expression in human mammary carcinoma." (PMID 37927213, 2023). "This study determined the role and mechanism of YY1 and HSF1 in FAM3C‐induced proliferation and migration of breast cancer cells." (PMID 30887707, 2019). "In human MDA‐MB‐231 breast cancer cell line, transforming growth factor‐β (TGFβ) up‐regulated FAM3C, HSF1 and YY1 expressions." (PMID 30887707, 2019). "Overall, these findings revealed that FAM3C stimulated the proliferation and migration of breast cancer cells by activating HSF1‐Akt pathway." (PMID 30887707, 2019). "Collectively, these findings in MDA‐MB‐231 and BT‐549 cell lines together suggested that FAM3C and TGFβ promoted the proliferation and migration of breast cancer cells via the activation of YY1‐HSF1 signalling axis." (PMID 30887707, 2019). "Clearly, developing high sensitive methods for the determination of circulating FAM3C protein level will shed light on the diagnosis and treatment of breast cancer." (PMID 30887707, 2019). "Particularly, the role of FAM3C in TGFβ‐induced Akt activation and cell proliferation/migration in breast cancer cells remains unrevealed." (PMID 30887707, 2019). "FAM3C silencing inhibited the migration of breast cancer cells in the absence or presence of TGFβ stimulation." (PMID 30887707, 2019). "Our previous studies have clearly demonstrated the role of shPCBP1-mediated EMT in the progression of mammary carcinoma in vivo and was therefore selected as an appropriate experimental context for further characterization of FAM3C/LIFR/STAT3 participation in the regulation of pathological features." (PMID 37927213, 2023). "Moreover, in human breast cancer tissues, FAM3C protein expressions are increased, and FAM3C activates YY1-HSF1 signalling axis to promote the proliferation and migration of breast cancer MDA-MB-231 and BT-549 cells." (PMID 37704682, 2023). "Unsurprisingly, the transcriptomic perturbations evoked by FAM3C-overexpression were found to closely resemble curated gene signatures relevant to lung carcinoma, breast carcinoma, and prostate carcinoma, based on enrichment analyses using the Human Disease Ontology (DO)." (PMID 36632230, 2023).
breast carcinoma (continued). "Additionally, gene ontology analysis was performed using the DAVID Knowledgebase, revealing a significant association between the shPCBP1/FAM3C/LIFR transcriptomic signature and phenotypic context involved in mammary carcinoma pathology." (PMID 37927213, 2023). "FAM3C, which is in the 1-Mb region of an Indel on SSC18 and associated with ADIFF, encodes Interleukin-Like Epithelial-Mesenchymal Transition Inducer for the proliferation and migration of breast cancer cells." (PMID 35565484, 2022). "Similarly, inhibition of HSF1 also blunted FAM3C‐ and TGFβ‐promoted proliferation and migration of human breast cancer BT‐549 cells." (PMID 30887707, 2019). "Generally, two FAM3C protein isoforms were detected in breast cancer cells and other cell types." (PMID 30887707, 2019). "In human breast cancer tissues, FAM3C, YY1 and HSF1 protein expressions were increased." (PMID 30887707, 2019). "FAM3C,14, 15 HSF123, 24 and YY133, 34 have been independently reported to be associated with breast cancer, and all of them could serve as potential diagnostic biomarkers and therapeutical targets." (PMID 30887707, 2019). "Fam3C, also known as Interleukin-like EMT inducer (ILEI), is an established regulator of the epithelial to mesenchymal transition and breast cancer stem cell phenotypes." (PMID 41247074, 2025). "FAM3C activates YY1 to induce HSF1 expression, which finally triggers the proliferation and migration of breast cancer cells by activating Akt." (PMID 30887707, 2019). "Clearly, the roles of FAM3C, YY1 and HSF1 in the pathogenesis of breast cancer and/or other cancers should be considered as a whole." (PMID 30887707, 2019). "FAM3C up‐regulates YY1 to induce HSF1 expression, finally activating Akt‐Cyclin D1 pathway to promote the proliferation and migration of breast cancer cells." (PMID 30887707, 2019). "YY1 silencing blunted FAM3C‐ and TGFβ‐triggered activation of HSF1‐Akt‐Cyclin D1 pathway, and proliferation and migration of breast cancer cells." (PMID 30887707, 2019). "In conclusion, FAM3C activated YY1‐HSF1 signalling axis to promote the proliferation and migration of breast cancer cells." (PMID 30887707, 2019). "Inhibition of HSF1 blocked TGFβ‐, FAM3C‐ and YY1‐induced proliferation and migration of breast cancer cells." (PMID 30887707, 2019). "FAM3C inhibition repressed TGFβ‐induced HSF1 activation, and proliferation and migration of breast cancer cells." (PMID 30887707, 2019). "In summary, this study revealed that FAM3C, YY1 and HSF1 are coordinated to promote the proliferation and migration of human breast cancer MDA‐MB‐231 cells." (PMID 30887707, 2019). "An increase in FAM3C expression due to excessive TGFβ production plays important roles in inducing YY1 and HSF1 expressions as observed in human breast cancer or other cancer tissues." (PMID 30887707, 2019). "Consistent with our results, recent investigations demonstrated that overexpression of FAM3C correlated with EMT and metastasis in breast cancer and colon cancer." (PMID 26498278, 2015). "Additionally, the FAM3 cytokine family includes an oncogenic member, TGFβ-modulated FAM3C/Interleukin-like EMT Inducer (ILEI), which can lead to the formation of breast cancer stem cells, accelerating the progression of breast cancer." (PMID 34488773, 2021). "This study aimed to determine whether and how FAM3C activated HSF1 transcription to promote the proliferation and migration of breast cancer cells." (PMID 30887707, 2019).
melanoma (9 papers, 2017 to 2023). A malignant, usually aggressive tumor composed of atypical, neoplastic melanocytes. "ILEI (FAM3C) mRNA is highly expressed in melanoma metastases." (PMID 35406721, 2022). "For example, we detected the presence of thrombospondin-1, which is involved in a melanoma epithelial-to-mesenchymal transition (EMT)-like process, or to protein FAM3C, and possibly related to EMT, tumor progression, and metastasis." (PMID 33467521, 2021). "In contrast to melanoma observation, compared to A549 spheroid cultures, higher basal intracellular expression of MITF in CD44+ and CD133+ spheroid cultures of H1299 cells were well correlated with their increased cellular FAM3C expression." (PMID 35563313, 2022).
Alzheimer disease (5 papers, 2020 to 2024). A progressive, neurodegenerative disease characterized by loss of function and death of nerve cells in several areas of the brain leading to loss of cognitive function such as memory and language. "Compared to the GWAS using global gray matter volume as the phenotype, our GWAS revealed additional signal in chromosome 7 (rs7776725), which was mapped to the intron of FAM3C and encodes a secreted protein involved in pancreatic cancer and Alzheimer’s disease." (PMID 39422662, 2024). "In post-mortem autopsies of patients with Alzheimer’s disease, FAM3C is decreased in brain sections." (PMID 38674105, 2024). "Another study evaluated the overexpression of human FAM3C in neuronal cells under the control of the mouse prion promoter to understand the mechanism of Alzheimer’s disease." (PMID 37713409, 2023). "However, some studies have indicated that in patients with Alzheimer's disease, Notch signaling and γ‐secretase activity are not influenced by FAM3C, which is inconsistent with the findings of our study." (PMID 39629744, 2024).
colorectal cancer (5 papers, 2015 to 2025). A primary or metastatic malignant neoplasm that affects the colon or rectum. "Increased FAM3C and MET copy numbers were tightly linked and correlated with increased gene expression and poor survival in human lung cancer and with extramural invasion in colorectal carcinoma." (PMID 33596971, 2021). "In addition, overexpression of FAM3C was detected in pancreatic cancer and colorectal cancer, suggesting important roles of FAM3C in the metastasis and progression of cancer." (PMID 26498278, 2015). "In colorectal cancer, transcriptional activation via H3K27 acetylation permits NUTM2A-AS1 to sequester miR-126-5p, leading to upregulation of FAM3C, while in glioma, its interaction with miR-376a-3p regulates YAP1 expression." (PMID 40903777, 2025). "In colorectal cancer, its transcriptional activation by H3K27 acetylation enables it to sequester miR-126-5p and upregulate FAM3C." (PMID 40903777, 2025). "In colorectal cancer, for example, H3K27ac enrichment at the NUTM2A-AS1 promoter is pivotal for its transcriptional activation, thereby enabling its function as a ceRNA for miR-126-5p and the consequent upregulation of FAM3C." (PMID 40903777, 2025).
gastric cancer (5 papers, 2022 to 2024). A primary or metastatic malignant neoplasm involving the stomach. "Bioinformatics analysis with TCGA data indicated that CD151 mRNA level was positively correlated with FAM3C level in gastric cancer and was inversely associated with overall survival of stomach cancer patients (P = 0.024)." (PMID 37056931, 2023). "Bioinformatics analysis using the data of stomach cancer patients from the Cancer Genome Atlas (TCGA) revealed that FAM3C mRNA level in gastric cancer tissues was much higher than that in the corresponding normal stomach tissues (P < 0.001)." (PMID 37056931, 2023). "Importantly, FAM3C was strongly expressed in TANs in human gastric cancer tissues and cancer emboli with IHC assays." (PMID 37056931, 2023). "Furthermore, TGFβ1 mRNA level was positively correlated with FAM3C level in gastric cancer (P = 0.002)." (PMID 37056931, 2023). "Furthermore, FAM3C level in tumors was related to TNM staging of gastric cancer although it was not significant (P = 0.063), and FAM3C level in tumors was inversely associated with cumulative survival of stomach cancer patients (P = 0.022)." (PMID 37056931, 2023). "In the gastric cancer cell lines MKN45 and AGS, knockdown of FAM3C reduces cell migration, and suppresses activation of the PI3K-Akt signaling pathway." (PMID 37704682, 2023).
lung carcinoma (5 papers, 2015 to 2023). "Third, protein-based analyses on tumor specimens and circulating EVs isolated from lung carcinoma donors detected an increasing level of FAM3C that is specifically associated with lung carcinoma progression." (PMID 36632230, 2023). "Here, we present several lines of evidence to support the notion that FAM3C is prominently involved in colonization of lung carcinoma." (PMID 36632230, 2023). "Aberrant expression of FAM3C in lung carcinoma cells enhances cellular transformation and promotes distant lung tumor colonization." (PMID 36632230, 2023). "Third, to further reinforce the findings from Co-IP assays, we also utilized an in situ Duolink proximity ligation assay (PLA) and confirmed the proximal co-localization of FAM3C with RalA in A549 parental and FAM3C_ox lung carcinoma cells." (PMID 36632230, 2023). "This was further corroborated by the reciprocal observations that H2170 FAM3C_ox cells expressed higher p-RalA, whereas FAM3C silencing in four FAM3C highly expressed lung cancer cell lines ablated expression of RalA phosphorylation (right)." (PMID 36632230, 2023). "Recently, a similar translational regulation pattern of FAM3C was observed in human lung cancer cell line A549." (PMID 26498278, 2015). "Second, distribution of FAM3C transcript is heterogenous across various cell types 26, and significant enrichments of FAM3C-positive populations are observed in lymph node and brain metastases of lung carcinoma patients." (PMID 36632230, 2023). "Though our study was pertinent in lung carcinoma, it may be relevant for other malignancies that highly express FAM3C, especially in EVs of cancer patients." (PMID 36632230, 2023). "Collectively, these analyses suggested that FAM3C is likely of tumor origin and may play a significant role in the disease progression of lung carcinoma metastasis." (PMID 36632230, 2023). "Furthermore, significantly higher mRNA expression of FAM3C in carcinoma tissues was observed as compared to the normal lung counterparts based on five independent lung carcinoma datasets." (PMID 36632230, 2023). "Intra- and extra-cellular FAM3C was found to be involved in biological processes such as signal transduction and cell–cell communication, which enhances tumorigenicity and metastasis in cancer, correlating with a shorter survival duration in patients with lung cancer." (PMID 35563313, 2022). "To dispel the notion that FAM3C interacts with RalA only at artificially high levels of protein expression, we repeated the experiment with FAM3C-high SKMES-1 lung carcinoma cells and confirmed the endogenous interaction of RalA and FAM3C." (PMID 36632230, 2023). "Given that the lack of correlation between FAM3C expression and its known receptor LIFR in lung cancer, it signifies the need to elucidate the underlying mechanisms of its signal transduction." (PMID 36632230, 2023).
pancreatic cancer (5 papers, 2015 to 2024). "The univariate analysis suggested that age, grade, T stage, N stage, number of positive lymph nodes, cancer status, tissue of origin, and FAM3C expression were risk factors for pancreatic cancer patients prognosis." (PMID 37704682, 2023). "Immunohistochemical staining was used to study the relationship between FAM3C expression and clinical characteristics of pancreatic cancer patients." (PMID 37704682, 2023). "In order to comprehensive exploration, we combined data from the clinical samples, TCGA and GTEx databases to analyze FAM3C expression in tumor and normal tissues of pancreatic carcinoma." (PMID 37704682, 2023). "Our study showed that the expression of FAM3C in pancreatic carcinoma tissues was significantly higher than normal tissues, and the high expression of FAM3C was significantly related to poor prognosis of pancreatic carcinoma patients." (PMID 37704682, 2023). "Whereas, the relationship between FAM3C and pancreatic cancer (PAAD) remains elusive." (PMID 37704682, 2023). "Furthermore, we evaluated the prognostic significance of FAM3C in pancreatic cancer and validated the role of FAM3C in PAAD by in vitro cellular assays." (PMID 37704682, 2023).
diabetes (4 papers, 2017 to 2025). "Under conditions with dysregulated glucose and lipid metabolism, serum FAM3C protein level might be a novel biomarker for predicting the risk of diabetes or cancer." (PMID 29285313, 2017). "This also suggested that circulating FAM3C could be a new biomarker for diagnosis and classification of diabetes, particularly in the era of precision medicine." (PMID 29285313, 2017).
prostate carcinoma (4 papers, 2017 to 2023). A carcinoma that arises from epithelial cells of the prostate gland. "Interestingly, FAM3C (or ILEI), another FAM3 family member, is highly expressed in patients with prostate cancer." (PMID 29357840, 2018).
esophageal cancer (3 papers, 2023 to 2025). A primary or metastatic malignant neoplasm involving the esophagus. "MiR-574-3p exerts tumor-suppressive effects in esophageal cancer by directly targeting FAM3C and MAPK1, thereby inhibiting cellular proliferation and invasive potential." (PMID 40746552, 2025). "MiR-574-3p represses the proliferation and invasion of esophageal cancer by regulating FAM3C and MAPK163." (PMID 37704682, 2023). "Furthermore, the expression of FAM3C mRNA in esophageal cancer tissues is significantly higher than that in normal tissues, and the high FAM3C expression group have worse prognosis." (PMID 37704682, 2023).